MARVELD2 (MARVEL domain containing 2)
Description:
Plays a role in the formation of tricellular tight junctions and of epithelial barriers (By similarity). Required for normal hearing via its role in the separation of the endolymphatic and perilymphatic spaces of the organ of Corti in the inner ear, and for normal survival of hair cells in the organ of Corti.
Synonyms: TRIC; FLJ30532; DFNB49; MARVD2; MRVLDC2
Tractability: Antibody: UniProt places it where antibodies can reach, with high confidence; UniProt predicts a signal peptide or a membrane-spanning region; its Gene Ontology location is reachable by antibodies, with medium confidence. PROTAC: UniProt records ubiquitination sites on it; ubiquitination databases record sites on it; its protein half-life has been measured.
Gene: Protein-coding gene on chromosome 5 (69,415,065 to 69,444,330, forward strand). Ensembl gene ENSG00000152939.
Subcellular location: Cell membrane; Cell junction, tight junction
Subcellular location (Human Protein Atlas): Cell Junctions
Gene Ontology:
Molecular function: protein binding
Biological process: bicellular tight junction assembly; cell-cell junction organization; establishment of endothelial barrier; sensory perception of sound
Cellular component: apical plasma membrane; basolateral plasma membrane; bicellular tight junction; cell junction; cytoplasm; cytoplasmic vesicle; plasma membrane; tight junction; tricellular tight junction; membrane; paranodal junction; Schmidt-Lanterman incisure
Genetic constraint (gnomAD): Loss-of-function variants: 36 observed, 47.86 expected, observed/expected ratio (o/e) 0.75, 90% interval 0.58 to 0.99. The upper end of that interval is the gene's LOEUF score, 0.99, which puts it in group 4 of 6, group 1 being the genes least tolerant of losing a copy. Missense variants: 540 observed, 655.33 expected, observed/expected ratio (o/e) 0.82, 90% interval 0.77 to 0.88. Synonymous variants: 221 observed, 247.04 expected, observed/expected ratio (o/e) 0.89, 90% interval 0.8 to 1.
Gene-disease validity (ClinGen):
ClinGen rates the evidence that MARVELD2 causes each of these diseases.
nonsyndromic genetic hearing loss (autosomal recessive): Definitive. A disease characterized by hearing loss that is not part of a larger syndrome.
Homologues: Orthologues: chimpanzee MARVELD2 (99% identical), macaque MARVELD2 (98% identical), pig MARVELD2 (89% identical), mouse Marveld2 (87% identical), rabbit MARVELD2 (87% identical), rat Marveld2 (85% identical), dog MARVELD2 (77% identical), tropical clawed frog marveld2 (66% identical), zebrafish marveld2a (56% identical), zebrafish marveld2b (55% identical), Drosophila melanogaster Su(Tpl) (15% identical), Caenorhabditis elegans ell-1 (9% identical). Paralogues in human: ELL (18% identical), ELL2 (17% identical), OCEL1 (15% identical), OCLN (15% identical), ELL3 (12% identical).
Diseases named in the same sentence as MARVELD2 in open-access papers:
MARVELD2 is named in the same sentence as 59 diseases in open-access papers, as found by Europe PMC text mining. Sharing a sentence is not in itself a finding about the gene and the disease. The quoted sentences say what the papers report.
deafness (13 papers, 2012 to 2025). An inherited or acquired condition characterized by the complete loss of the ability to hear from one or both ears. "Mice homozygous for the knock-in pathogenic Marveld2 variant exhibited syndromic deafness with rapid progressive degeneration of the hair cells, increased body and organ weights, and abnormal tTJs with vestibular disturbance." (PMID 40244166, 2025). "Marveld2−/− mice develop very severe hearing loss early in life and rapidly progress to total deafness, with a large early loss of outer hair cells through apoptosis." (PMID 39078259, 2024). "This study aimed to analyze the molecular, epidemiological, and clinical phenotypes of the members of a family with deafness carrying the MARVELD2 c.663G>A nonsense mutation." (PMID 39698467, 2024). "This study expands the spectrum of MARVELD2 mutations that cause nonsyndromic hearing loss and provides insights into the molecular pathogenesis underlying deafness." (PMID 39698467, 2024). "To date, only eleven families of Pakistani, three of Roma and one of Iranian origin with MARVELD2-associated deafness are known in the existing literature." (PMID 25885414, 2015). "In humans, mutations in the MARVELD2 gene lead to nonsyndromic, bilateral, prelingual moderate to profound deafness." (PMID 25885414, 2015). "Targeted next‐generation sequencing was used to identify novethreel variants of MARVELD2, and online tools were used to analyze variants' pathogenicity, which could further expand the spectrum of deafness gene mutations." (PMID 39078259, 2024). "We screened 218 deafness genes using next‐generation sequencing and Sanger sequencing and found compound heterozygous mutations in MARVELD2, and therefore hypothesized that hereditary factors may be the major cause of hearing loss in the probands." (PMID 39078259, 2024). "Future studies focused on other Roma subpopulations throughout Europe (particularly in the Mediterranean area) may further illuminate the relative importance of MARVELD2 gene as a deafness cause in Roma." (PMID 25885414, 2015). "However, the only obvious phenotype of the MARVELD2 mutant alleles is deafness." (PMID 39698467, 2024). "Prior Marveld2−/− mice studies have demonstrated early onset deafness with multiple-organs disorder and vestibular involvement." (PMID 40244166, 2025). "The phenotypes of six Slovak patients with MARVELD2 related deafness correspond to available literature data." (PMID 25885414, 2015). "So far, MARVELD2 positive deafness cases are only known from Pakistan, Iran and Czech Republic (Central Europe), not from India." (PMID 25885414, 2015). "Our study provides the first record of MARVELD2 related deafness in Slovakia and Hungary." (PMID 25885414, 2015). "Sanger sequence of its coding regions plus intron-exon boundaries (∼100 bp) revealed no pathogenic variants but only a common polymorphism (rs1185246, MAF = 0.477), suggesting that MARVELD2 was unlikely to be involved in the deafness in this family." (PMID 24312468, 2013).
breast carcinoma (9 papers, 2018 to 2024). "For the two risky genes, the prognostic value of DYNC2I2 in breast cancer has been studied in former works, while that of MARVELD2 has not." (PMID 34604090, 2021).
hearing loss (7 papers, 2013 to 2025). "The two most common variants known to cause hereditary hearing loss among Roma have been identified: the first is in the GJB2 gene, c.71G>A (p.W24*), which is also found in India, and the other is c.1331+2T>C in MARVELD2, described originally in Pakistani families." (PMID 32847582, 2020). "The BDP1 gene maps in a hearing loss locus DFNB49, 2Mb away from MARVELD2, a gene already known to be involved in hearing loss but containing no predicted pathogenic mutations in this family." (PMID 24312468, 2013). "MARVELD2 (OMIM ID:610572), located in the DFNB49 locus, which encodes a tight junction protein tricellulin playing an important role in the sensory epithelial barrier of the inner ear, may contribute to nonsyndromic autosomal recessive hereditary hearing loss." (PMID 39078259, 2024).
hepatocellular carcinoma (6 papers, 2016 to 2024). A malignant tumor that arises from hepatocytes. "In consistent with this, MARVELD2 a membrane protein associated with tight junction between cells, and it was reported to be a prognostic gene in hepatocellular carcinoma (HCC) and cholangiocarcinomas." (PMID 28796819, 2017). "Recent studies have further revealed that MARVELD2 is frequently overexpressed in hepatocellular carcinoma cells but downregulated in pancreatic carcinomas cells." (PMID 32528944, 2020).
lung carcinoma (3 papers, 2021 to 2026). "For example, the hypermethylation of site 5:68711681 was linked with the differential expression of MARVELD2 in Lapatinib-sensitive and -resistant lung cancer cell lines." (PMID 34356665, 2021).
nonsyndromic hearing loss (1 paper, 2024). "The MARVELD2 gene is located on chromosome 5q13.2 and is associated with autosomal recessive nonsyndromic hearing loss (OMIM: # 610572)." (PMID 39698467, 2024).
sensorineural hearing loss (1 paper, 2024). "As of this writing, 13 MARVELD2 mutations that may be associated with sensorineural hearing loss have been reported in Pakistani, Slovak, Czech Roma, Hungarian Roma and Chinese families, and 2 other mutations that have not yet been reported were identified in our study." (PMID 39078259, 2024).
skin cancer (1 paper, 2020). "MARVELD2 has been reported to contribute to the classification of multiple tumor subtypes at methylation level, including skin cancer." (PMID 32528944, 2020).
squamous cell carcinoma (1 paper, 2020). A carcinoma arising from squamous epithelial cells. "Early in 2011, the expression of MARVELD2 is evidently decreased in every stage of squamous cell carcinoma." (PMID 32528944, 2020).
cancer (37 papers, 2013 to 2026). A tumor composed of atypical neoplastic, often pleomorphic cells that invade other tissues. "Hence, abnormal MARVELD2 expression always associates with various types of carcinoma pathogenesis." (PMID 32528944, 2020). "With regard to MARVELD2, pathogenic mutations of this gene cause autosomal recessive non-syndromic hearing loss (DFNB49), nevertheless, little is known about the roles of MARVELD2 in cancer." (PMID 34604090, 2021). "It is noticed that the coefficients of MARVELD2 and XRCC6BP1 are negative, indicating that these two gene have tumor-repression ability while the other eight genes are cancer genes." (PMID 28796819, 2017).
tumor (28 papers, 2012 to 2026). "Genes involved in cell growth, survival and resistance to apoptosis (MAPK2,MAPK5) as well as genes associated with cell-cell adhesion (MARVELD2, CTNDD1) were highly upregulated in cluster 3, consistent with tumor resistance and patient outcome in this group." (PMID 37559718, 2023). "In consideration of the relationship between gene expression and methylation, this evidence could suggest the methylation diversity of MARVELD2 in different tumor types." (PMID 32528944, 2020). "On the basis of our results, MARVELD2 was predicted to show methylation diversity in tumor cells." (PMID 32528944, 2020). "Methylation of the MARVELD2 gene could be used to classify multiple different tumor types." (PMID 32528944, 2020). "Cluster 1 was characterized by upregulation of tumor-suppressing genes: HNF1B, CCNDBP1, PATJ, EPB41L3, MARVELD2, PTEN in conjunction with cell-cycle genes – GSPT1, GPR19, EAPP, KIT, CDKL1, and stem cell markers – RBBP5, NANOG, NCSTN, ERG, including quiescent stem cell markers—FOXP1, SMARCA2." (PMID 36348001, 2022).
MARVELD2 also shares sentences with these, for which no sentence is quoted: neurodegenerative disease (7 papers); Huntington disease (6); Alzheimer disease (4); neuropathies (4); adenocarcinoma (3); autosomal recessive nonsyndromic deafness (3); infection (3); pancreatic cancer (3); pancreatic ductal adenocarcinoma (3); amyloid diseases (2); cardiovascular disease (2); endometrial cancer (2); gastric cancer (2); glioma (2); myopathies (2); neuroblastoma (2); retinal degeneration (2); acute promyelocytic leukemia (1); Arrhythmia (1); Bardet-Biedl syndrome (1); brain malformations (1); breast invasive carcinoma (1); Burkitt lymphoma (1); cholangiocarcinoma (1); colon cancer (1); colorectal cancer (1); developmental delay (1); endometriosis (1); Ewing sarcoma (1); glioblastoma (1).
A further 18 diseases each share a sentence with MARVELD2 in 1 paper.